FAS (Fas cell surface death receptor)
Diseases named in the same sentence as FAS in open-access papers (continued):
Sharing a sentence is not in itself a finding about the gene and the disease.
cancer (continued). "An additive gene–gene interaction was observed between FAS-1377G/A and FASL-844T/C polymorphisms and decreased risk of cancer, suggesting that both polymorphisms may be active in the same causal pathway." (PMID 24014103, 2013). "In our analysis, FAS/CD95 was also lower in resistant NSCLC compared to sensitive carcinomas." (PMID 12177790, 2002). "The apoptotic factor FAS/CD95 was less expressed than in sensitive carcinomas." (PMID 12177790, 2002). "However, the FAS expression level does not necessarily predict cancer cell susceptibility to apoptosis." (PMID 38791085, 2024). "FASLG/FAS signaling could induce apoptosis in various cancers." (PMID 35754839, 2022). "T-cell apoptosis could be triggered by up-regulating FAS/FASL system in cancer cells." (PMID 36248961, 2022). "However, cancer cells increase de novo FAS to meet energy demands under metabolic stress." (PMID 36290817, 2022). "Our results suggest that etoposide induces an increase in the expression of apoptosis‐associated proteins such as FAS and NOXA genes can be part of the molecular mechanism associated with this phenomenon, and in fact, DNA damage induces the expression of FAS in other cancer cells." (PMID 35538662, 2022). "However, it is unknown whether restoring FAS expression alone is sufficient to suppress csolorectal-cancer development." (PMID 35053524, 2022). "The AICD of T lymphocytes was a FASL-dependent process and accumulated evidences have demonstrated that the elevated expression of FASL could counterattack FAS-sensitive TILs, which may lead to immune privilege and then weaken the cancer cells' sensitivity to chemotherapy." (PMID 33403042, 2021). "Therefore, we analyzed the possibility that miR-181c might play an anti-cancer regulatory role in ES cells by targeting FAS." (PMID 29563856, 2018). "Interestingly, all four target genes were covered, or at least partially covered, by the five signaling pathways identified: BCL2L1 and IGF1R are involved in PI3K-Akt signaling, IGF1R and MAPK8 in FoxO signaling, IGF1R and FAS in proteoglycans in cancer, and MAPK8 and FAS in MAPK signaling." (PMID 30497474, 2018). "Thus, other factors than USFs may have a more dominant role for the regulation of FAS expression in cancer cells." (PMID 25741280, 2015). "Thus, subjects carrying both FAS-1377AA and FASL-844CC could be at higher risk for developing cancer than those carrying either FAS-1377AA or FASL-844CC alone." (PMID 24014103, 2013). "The FAS/FASL system may have two opposite effects on cancer." (PMID 23326385, 2013). "Moreover, there is growing evidence indicating that potentially functional polymorphisms of FAS/FASL system could act as low susceptibility factors and modify the phenotype of cancer." (PMID 23951214, 2013). "The five most significant BioCarta pathways were first multivalent nuclear factor, FAS signaling pathway (CD95), p38 MAPK signaling pathway, control of skeletal myogenesis by HDAC and calcium/calmodulin-dependent kinase (CaMK), role of BRCA1, BRCA2, and ATR in cancer susceptibility." (PMID 21836821, 2011). "Our comprehensive analysis revealed that PLEK2 expression was significantly associated with various immune regulatory genes across multiple cancer types, including CD276 (B7-H3), CD274 (PD-L1), and FAS." (PMID 39546161, 2024). "Decreased use of glucose, leading to a reduced production of acetyl-CoA by cancer cells cultured at pH 6.5 compared to pH 7.4.Concomitant use of fatty acid oxidation (FAO) and synthesis (FAS) under acidosis through downregulation of ACC2." (PMID 39355125, 2024). "This FAS/FASL system plays a critical role in the immune system, as well as in the development and progression of certain diseases such as cancer." (PMID 36836481, 2023).
cancer (continued). "Overexpression of FA biosynthetic genes including FAS, ACC, SREBP1, and LPL have been demonstrated in several cancer phenotypes." (PMID 38020549, 2023). "Fatty acid synthesis (FAS) and its counterpart fatty acid oxidation (FAO) are efficient alternative energy sources for cancer cells." (PMID 36290817, 2022). "The results of immunohistochemistry (IHC) in the Human Protein Atlas (HPA) database showed that compared with normal tissues, ENOPH1, ACAT1, ALDH4A1, FAS, and ASPG are downregulated in cancer tissue than in normal tissue." (PMID 35992263, 2022). "FAS, C16orfS4, FBXO31, ACSS3, ZCCHC8 and THBS3 were found to help the metastatic cancer cells survive from the immune surveillance." (PMID 35685372, 2022). "In FAS knockout cells, restoring the NOTCH1 intracellular domain stimulated cancer spheroid formation." (PMID 35249111, 2022). "In comparison, FADD in 12 cancer types, FASLG in 3 cancer types, RIPK1 in 19 cancer types, TLR3 in 25 cancer types, TNF in 11 cancer types, FAS in 22 cancer types, MLKL in 15 cancer types, and RIPK3 in 12 cancer types had homozygous deletions." (PMID 35748782, 2022). "We examined the stemness ability of FAS−/− SAS cells and found that FAS depletion also decreased OCT4 reporter activity and prevented cancer spheroid formation." (PMID 35249111, 2022). "The genes involving cell cycle control, DNA replication, apoptosis, senescence and autophagy in cancer pathways including CDK4, E2F1, Bax, CDKN1A, GADD45A, FAS, GABARAPL2, and SQSTM were significantly upregulated." (PMID 34305605, 2021). "More studies in larger patient cohorts are needed to fully understand the FAS and FASLG pathways and their possible role in cancer progression or suppression." (PMID 32606315, 2020). "Of these, HMGA2 was reported participating in the proliferation of many cancer types, and MMP7 was found affecting the apoptotic process mediated by FAS/FASL system as well as N-cadherin." (PMID 32874135, 2020). "We found in this study that mRNA levels of FAS and FASL increased in cancer tissues compared to the control with the increasing severity of LC, which was not consistent with the protein expression." (PMID 33415169, 2020). "Accordingly, NO disrupts the transcriptional repressor activity of YY1 not only on FAS but also on DR5, up-regulates its expression and sensitizes cancer cells to TRAIL-induced apoptosis." (PMID 32370259, 2020). "Among those we found TNFSF13: FAS and CCL5: CCR5, two pairs of ligands/receptors that are known to play a role in AML and other cancers." (PMID 32399572, 2020). "The proper use of HI NK cells for cancer immunotherapy should efficiently eliminate HCC cells that express upregulated of NKG2D ligands and FAS, presumably similar to SNU398 cells." (PMID 30925759, 2019). "We further investigated the expression of alternative genes through which T cells can induce cytolysis of cancer cells, including CD95-CD95L (FAS-FASLG) and TRAIL-TRAILR (TNFSF10, TNFRSF10A/B)." (PMID 29515971, 2018). "Four target genes (BCL2L1, IGF1R, MAPK8, and FAS) and 5 signaling pathways (PI3K-Akt, FoxO, MAPK, pathways in cancer, and proteoglycans in cancer) were identified." (PMID 30497474, 2018). "For the same expected Wernicke’s region, FAS and CAT detected significantly less cases in the cancer group than did SSC (p FAS and CAT detected significantly fewer cases in the healthy volunteer group than did SSC (p < 0.0001 by McNemar’s test)." (PMID 28935966, 2017). "Our results clearly demonstrate that SSC is superior to FAS and CAT at localizing Wernicke’s area, with a significantly higher activation rate in both cancer patients and controls." (PMID 28935966, 2017).
cancer (continued). "CD 4+ T cells (Th1) can kill cancer cell directly, for example, through FAS- or TRAIL-dependent pathway, while CD 8+ T cell is more effective in killing cancer cells." (PMID 28724377, 2017). "Western blot analysis showed that BV treatment clearly increased DR3 and DR6 expression in a concentration dependent manner in both cells, and expression of FAS in Ca Ski and DR4 in C33A cancer cells was increased by BV." (PMID 25730901, 2015). "Aberrant promoter methylation of FAS and FADD gene were exposed in different types of human cancers." (PMID 25129245, 2014). "Aberrant expression of FAS and/or FASL has been detected in many human cancers and appears to be a feature of the malignant phenotype." (PMID 24587306, 2014). "MiR-196b-5p is dysregulated in many malignancies, has been related to cancer prognosis, and targets c-myc, ERG, MEIS1, FAS, ABL1, BCL-2 and several HOX genes." (PMID 25329796, 2014). "It has been reported that the aberration of expression of FAS and/or FASL results in cancer cells resisting the killing of T lymphocytes and is related to many human tumors." (PMID 24086353, 2013). "Another well-studied key gene in cancer is the 50th gene on the SAM list, FAS, a member of the TNF receptor superfamily." (PMID 19691856, 2009). "It is known that, most—if not all—types of cancers are resistant to cellular apoptosis through FAS/FASL, even when overexpressing FAS receptor on their cell membrane." (PMID 37382757, 2024). "Our exploration revealed a significant increase in EV secretion carrying oncogenic proteins (TMEM205, STAT5, and FAS) in adipose and uterine tissues/serum samples from obese EC patients compared to control (without cancer)." (PMID 39414985, 2024). "Negative correlation between methylation and expression of FAS has been reported in several cancers such as colon cancer, small cell lung carcinoma and a variant of T-cell lymphoma, Sezary Syndrome." (PMID 37569529, 2023). "In addition to CCND1, several other cancer-relevant genes, including MCL1, BCL2L1, CDC25, FAS, and HIF1A, were among the common genes." (PMID 36807142, 2023). "We also tested the observed survival difference based on FAS expression in the non-overlapping 81-sample cohort from the Strategic Partnering to Evaluate Cancer Signatures (SPECS) initiative and found similar results." (PMID 37569529, 2023). "The mutations in FAS and FASL genes reduce the risks of certain types of cancer but not the others, indicating that T cell apoptosis behaves differently in different cancers." (PMID 36248961, 2022). "Analysis of human cancer genomics database revealed that the FAS locus is not focally amplified across a dataset of 3131 tumors, suggesting that FAS is unlikely an oncogene." (PMID 35053524, 2022). "The antigen-negative cancer cells can be targeted via FAS and Fas Ligand axis, independent of presenting death receptors by the cancer cell." (PMID 36499331, 2022). "Survival analysis showed that CNVs of TNF in 22 cancer types, TLR3 in 10 cancer types, RIPK1 in 9 cancer types, FAS in 8 cancer types, FADD in 8 cancer types, RIPK3 in 7 cancer types, MLKL in 6 cancer types, and FASLG in 5 cancer types were significantly associated with overall prognosis." (PMID 35748782, 2022). "It is worth studying the regulatory mechanism by which FAS regulates pyrimidine ribonucleotide metabolism in OSCC cells, which may provide an opportunity for treating cancers with aberrant metabolism." (PMID 35249111, 2022). "Meanwhile, homozygous CNV analysis showed that FADD in 22 cancer types, FASLG in 25 cancer types, RIPK1 in 22 cancer types, TLR3 in 15 cancer types, TNF in 23 cancer types, FAS in 15 cancer types, MLKL in 12 cancer types, and RIPK3 in 17 cancer types had homozygous amplifications." (PMID 35748782, 2022). "In addition, they have been reported to increase the expression of death-inducing receptors FAS and TRAIL-R2 on cancer cells enhancing the death of cancer cells by NK cells." (PMID 34957134, 2021).
cancer (continued). "GSEA indicated that multiple cancer signaling pathways (mTOR pathway, GSK3 pathway, EIF4 pathway, CHREBP2 pathway, MET pathway, NFAT pathway, FAS pathway, EDG1 pathway, AKT pathway, and CTCF pathway) were differentially enriched in YTHDF2 increased expression phenotype." (PMID 33102202, 2020). "In addition, the integrative results of GO, KEGG, and GSVA revealed some cancer-specific pathways, such as cell adhesion, HIF-1 signaling pathway and FAS signaling pathway, supporting the reliability and accuracy of our present in silico analyses." (PMID 30984247, 2019). "Since FAS/FASL pathway plays a critical role in apoptosis, this study might provide novel information for prognosis and secondary as well as tertiary cancer prevention of these patients." (PMID 26858129, 2016). "Previous studies suggested that the two FAS or FASL polymorphisms were not in a linkage disequilibrium and these polymorphisms had a joint effect on cancer risk, and the combined FAS/FASL genotypes were associated with a significantly increased risk of SCCHN." (PMID 26858129, 2016). "Finally, at 96h, the up-regulated module is revealed, including FAS and the transcription factor NFKB-related genes, the latter being aberrantly activated in various cancers." (PMID 26143641, 2015). "The combination treatment further increases the sensitivity of carcinoma cells to apoptosis through FAS and TRAIL receptors but does not change the sensitivity of normal non-malignant epithelial cells." (PMID 26703577, 2015). "FAS lacking exon 6, which is a more frequent event in cancer, yields a soluble FAS protein with anti-apoptotic activity." (PMID 23758675, 2013). "However, 5-Aza has proven to be effective in re-establishing caspase-8 expression in cancer cells, restoring their sensitivity to TRAIL-, anti-FAS-, and drug-triggered apoptosis." (PMID 21108789, 2010). "Noteworthy were a number of hub genes like TLR4, FAS, HLA-DQB1, HLA-DQA1, F2, HLA-C, IFNAR1, which link complex diseases related to metabolic, immunological, infectious, cardiovascular, neuro-psychiatric disorders and cancer." (PMID 18782426, 2008). "Indeed, many cancers have increased expression of enzymes that are inhibited by AMPK, such as FAS and mTOR." (PMID 17623090, 2007). "However, this postulation is not supported by several studies that showed that FAS can promote progression and metastasis in various cancers." (PMID 39416461, 2024). "However, the oncogenic role of FAS tumorigenesis and cancer progression has not been studied in OSCC." (PMID 35249111, 2022). "Thus, the polymorphism may affect FASL expression followed by subsequent FAS/FASL signaling, leading to apoptosis of cancer cells." (PMID 33639675, 2021). "The joint effects of the two FAS polymorphisms on risk of CRC were more pronounced among the subgroups with age >60 years, female, never smokers, never drinkers, having no family history of cancer, and CRC with intermediate grade and with Dukes C and D stage." (PMID 26759270, 2016). "However, FAS knockout cells could not colonize in distant organs to form metastases upon intravenous injection, which hinted at the cancer stemness function of the FAS receptor." (PMID 35249111, 2022). "DR4 and FAS are negative and TGF-β1 is a positive predictor of cancer-specific death." (PMID 38791085, 2024).
infection (123 papers, 2008 to 2025). The state of being infected such as from the introduction of a foreign agent such as serum, vaccine, antigenic substance or organism. "In the present study we report, for the first time, a family cluster of diseased persons presenting the infection across three generations associated with FAS -670A/G polymorphism." (PMID 29379480, 2017). "Previous studies have demonstrated that mice with inactivating mutations in FAS (lpr) or FASL (gld) have trouble controlling infections with West Nile virus, influenza virus, herpes simplex virus-1, herpes simplex virus-2, and mouse hepatitis virus." (PMID 25873756, 2015). "The EFNA5 and FAS genes were downregulated in MKN-28 cells only after 2-h infection with the H. pylori wt strain." (PMID 37193047, 2022). "Before infection, the expression of the FAS gene in the liver of fish in 2–8‰ treatments was significantly higher than that in fish in control, 0.5 and 1‰ treatments." (PMID 34305652, 2021). "As expected, we observed the percentages and cell numbers of GC B cells (FAS+GL7+) were markedly diminished in Ddb1-TaKO mice compared with WT mice at day 8 after infection." (PMID 34526995, 2021). "Like HIV Nef protein, EBV proteins BHRF1 and BZLF1 have been reported to protect EBV-infected cells from cell death by inhibiting the expression of TNFR1 or FAS at the first infection stage during the lytic phase." (PMID 30133498, 2018). "These cytokines (e.g., CCL8, FAS, and IL-6) begin to see significant expression in fatal cases starting at 4–5 days post-infection and are sustained through to the end of infection." (PMID 28930167, 2017). "The genes encoding FAS and TNFR2 were also highly expressed during infection, together with genes whose products are involved in TNF and NFκB signaling." (PMID 27982111, 2016). "Our data show that leukocytes from the patient with milder infection expressed a higher level of FAS mRNA compared to the patient with fatal ehrlichial infection and healthy controls." (PMID 22607204, 2012). "In the FAS signaling pathway, DTGs were significantly upregulated in the subacute phase (days 14 and 28 pi) and the beginning of the chronic phase (day 70 pi) of infection." (PMID 35056627, 2022). "These innate immune parameters (i.e., cytokines, LGLs/CD8+FAS+ cells) that are present during the first week of infection are key to defining differences in infection outcomes and could be used in therapeutic interventions to reduce disease severity in susceptible populations." (PMID 29677149, 2018). "Results showed that both FAS and FASL mRNA levels were markedly upregulated following infection, with expression significantly elevated from 24 h through 72 h (p < 0.05)." (PMID 41294830, 2025). "The upregulation of genes upstream of the cellular apoptosis such as FAS and SHISA5 enhanced the programmed death of the infected cell resulting in reducing inflammation, infection elimination, and prompt tissue repair." (PMID 38394169, 2024). "Three death receptors (TNFRSF1A, FAS, and TNFRSF10) were expressed at higher levels after mutant infection." (PMID 37513744, 2023). "The necroptosis pathway is triggered during pathogen infection and cellular damage by activation of specific death receptors including TNF receptor, FAS, and TLR3." (PMID 36619743, 2022).